PANX1 (pannexin 1)
Diseases named in the same sentence as PANX1 in open-access papers (continued):
Sharing a sentence is not in itself a finding about the gene and the disease.
asthma (3 papers, 2022 to 2025). "Firstly, Panx1 inhibited asthma pathogenesis by facilitating immune tolerance of Treg-Teff cell crosstalk via adenosine signaling." (PMID 40909173, 2025). "Excessive ATP release into ASL from patients with asthma signals inflammation and blocking Panx1 channels prevented airway hyperreactivity in an asthmatic mouse model." (PMID 41303221, 2025). "Recently, PANX1 expression was found to be important in suppressing airway inflammation in the asthma mouse model, and the knockdown of PANX1 resulted in increased airway inflammation." (PMID 35884429, 2022). "Clinical data reveal decreased Panx1 mRNA in peripheral blood mononuclear cells (PBMC) of pediatric asthma patients, while CD4+ T cell-specific Panx1 KO mice showed exacerbated House Dust Mite (HDM)-induced airway inflammation reversible upon Panx1 reconstitution." (PMID 40909173, 2025).
autism spectrum disorder (3 papers, 2019 to 2024). A spectrum of developmental disorders that includes autism, and Asperger syndrome. "Dysfunctional paracrine signaling through Pannexin 1 (PANX1) channels is linked to several adult neurological pathologies and human germline PANX1 variants have been associated with severe neurological deficits and autism spectrum disorder." (PMID 38212304, 2024). "Brain enriched, autism spectrum disorders (ASDs)-associated single nucleotide polymorphisms (SNPs) have been associated with changes in PANX1 expression levels." (PMID 32737184, 2020). "Moreover, single nucleotide polymorphisms affecting Panx1 expression levels have been implicated in autism spectrum disorder." (PMID 31118206, 2019). "The potential role of PANX1 in human brain development is further supported by a loss-of-function human germline PANX1 variant in a patient with severe neurological deficits, and by PANX1 and PANX2 single nucleotide polymorphisms implicated in autism spectrum disorder." (PMID 38212304, 2024).
autoimmune disease (3 papers, 2020 to 2025). A disorder resulting from loss of function or tissue destruction of an organ or multiple organs, arising from humoral or cellular immune responses of the individual to their own tissue constituents. "This review underscores the need for further research into Panx1’s molecular mechanisms and the development of targeted interventions to effectively address inflammatory and autoimmune diseases with precision and efficacy." (PMID 40978734, 2025). "The relevance of Panx1 also extends to autoimmune disorders such as multiple sclerosis and rheumatoid arthritis." (PMID 40978734, 2025). "Panx1 has emerged as a promising therapeutic target in a wide range of inflammatory and autoimmune diseases due to its role in extracellular ATP release and the activation of inflammatory pathways." (PMID 40978734, 2025). "Current studies indicate that Panx1 modulation may offer significant therapeutic benefits across a wide range of inflammatory and autoimmune diseases." (PMID 40978734, 2025). "Because the removal of apoptotic cells by macrophages is critical to suppress inflammation and autoimmune diseases, stimulating local macrophages by ATP and related nucleotides released through PANX1 channels should be a biologically important process in apoptosis." (PMID 33052098, 2020). "Recently, PBN has drawn interest as a candidate drug for repositioning for medical applications, including IBD, autoimmune diseases, neuroinflammation, and cardiovascular diseases, based on the finding that PBN inhibits pannexin-1 (Px1) channels." (PMID 41304792, 2025). "In addition, Panx1 regulates the osteogenic differentiation of mesenchymal stem cells through p38 MAPK phosphorylation, highlighting its broader role in autoimmune diseases affecting bone tissue." (PMID 40978734, 2025).
cardiac arrhythmias (3 papers, 2016 to 2022). Any disturbances of the normal rhythmic beating of the heart or MYOCARDIAL CONTRACTION. "Despite the knowledge gap in the regulation of these channels, current evidence indicates that HCs and Panx1 channel activation can enhance the risk of cardiac arrhythmias." (PMID 33383853, 2020). "Despite the gap in knowledge concerning the regulation of HCs and Panx1 channels and their impact in the heart (see Section 2), evidence indicates that the activation of these channels can be pro-arrhythmic (see Section 3) and enhance the risk of cardiac arrhythmias (see Section 5)." (PMID 33383853, 2020). "In this context it would be interesting to examine the efficacy of pharmacological blockade of CxHC and pannexin-1 channels, including specific inhibitors (e.g., Gap19, Gap26, Gap27), to prevent development of cardiac arrhythmias." (PMID 35163340, 2022). "P2X7R and Panx1 are shown to participate in neutrophil activity and recruitment, as well as IL-1β release in a study focusing on chronic obstructive pulmonary disease (COPD)." (PMID 27445679, 2016).
Cognitive impairment (3 papers, 2021 to 2024). Abnormal cognition is characterized by deficits in thinking, reasoning, or remembering. "Nevertheless, our finding showing impaired long term reference memory in both Panx1f/f and global Panx1 KO support the notion that ELS leads to cognitive impairment later in life." (PMID 39024558, 2024). "We identified that Pannexin-1 channel opening contributes to the high serological ATP levels, and ATP in the circulation could be used as a biomarker of HIV-associated cognitive impairment." (PMID 35883688, 2022).
Crohn disease (3 papers, 2021 to 2025). A gastrointestinal disorder characterized by chronic inflammation involving all layers of the intestinal wall, noncaseating granulomas affecting the intestinal wall and regional lymph nodes, and transmural fibrosis. "This study for the first time identifies the mechanism by which herb-partitioned moxibustion (at CV 6 and ST 25) may inhibit the abnormal activation of the NLRP3 inflammasome by inhibiting the P2X7R-Pannexin-1 signaling pathway in Crohn’s disease rats." (PMID 34043726, 2021).
cyst (3 papers, 2023 to 2026). A sac-like closed membranous structure that may be empty or contain fluid or amorphous material. "Apical ATP release is elevated in PKD1-deficient cyst-forming cells following pharmacological induction of HIF-1α and attenuated by two Pannexin-1 inhibitors, Probenecid and Brilliant Blue FCF (BB-FCF)." (PMID 42117913, 2026). "In conclusion, HIF-1α promotes Pannexin-1 expression in cyst-lining cells, facilitating directional ATP release into the cyst lumen and driving ATP-dependent cyst expansion." (PMID 42117913, 2026). "Shum and colleagues reported that PANX1 was preferentially enriched at the apical membrane of polarized MDCK cells grown as monolayer sheets or cyst‐like spheroids." (PMID 37024297, 2023). "The treatment of mice with the non-selective Panx1 blocker Probenecid reduced ATP release and slowed renal cyst development by improving epithelial transport across the cyst epithelium, thus demonstrating that Panx1 could be a new target for the treatment of ADPKD." (PMID 40430343, 2025).
endotoxemia (3 papers, 2019 to 2024). "We demonstrated that hepatic PANX1 deficiency exacerbated LPS‐induced endotoxemia and dysregulated the immune response in the mouse LT model." (PMID 35593197, 2022). "We observed significantly fewer CD4+CD8+ double‐positive (DP) thymocytes in the thymus of the Panx1−/‐ mice than in the WT mice after LPS stimulation, suggesting that Panx1 deficiency leads to more serious thymic involution in a mouse model of endotoxemia." (PMID 35593197, 2022). "To study whether IL‐33 could alleviate the hyperinflammation caused by PANX1 deficiency during endotoxemia, we pretreated the Panx1−/− → WT mice with recombinant IL‐33 (rIL‐33) 12 h before LPS injection." (PMID 35593197, 2022). "Therefore, to directly examine the role of PANX1 in endotoxemia and liver injury, we utilized Panx1‐deficient (Panx1−/−) mice." (PMID 35593197, 2022). "Recombinant IL‐33 treatment rescued LPS‐induced endotoxemia by increasing the numbers of liver‐infiltrating ST2+ Tregs and attenuating the cytokine storm in hepatic PANX1‐deficient mice." (PMID 35593197, 2022). "In the present study, we showed a protective role of the hepatic PANX1‐IL‐33 axis in LPS‐induced endotoxemia, which supplemented our previous research." (PMID 35593197, 2022). "In this study, we found that the PANX1‐IL‐33 axis played a protective role against LPS‐induced endotoxemia by promoting the resolution of hyperinflammation." (PMID 35593197, 2022). "In conclusion, our findings revealed that the hepatic PANX1–IL‐33 axis protects against endotoxemia and liver injury by targeting ST2+ Tregs and promoting the early resolution of hyperinflammation." (PMID 35593197, 2022). "To study the role of hepatic PANX1 in endotoxemia and fully simulate clinical practice, we generated an orthoptic mouse LT model using WT mice or Panx1−/− mice as donors and recipients, respectively." (PMID 35593197, 2022). "In LPS‐induced endotoxemia, hepatic PANX1 controlled IL‐33 synthesis and secretion via the ATP‐P2X7 pathway, thus targeting ST2+ Tregs and promoting the resolution of hyperinflammation." (PMID 35593197, 2022). "We showed that the adenosine triphosphate‐P2X7 pathway regulated the hepatic PANX1–IL‐33 axis during endotoxemia in vitro and in vivo." (PMID 35593197, 2022). "Based on these findings, PANX1 in hepatocytes exerted a protective effect against endotoxemia and related liver injury." (PMID 35593197, 2022). "In this study, we found that the PANX1–IL‐33 axis played a protective role in LPS‐induced endotoxemia by regulating host adaptive immunity and promoting the resolution of hyperinflammation." (PMID 35593197, 2022). "To study the immune landscape of Panx1−/− mice with endotoxemia, we measured the levels of cytokines, chemokines and various immune cells in the host circulation." (PMID 35593197, 2022). "According to our results, the Panx1−/‐ mice exhibited a more severe cytokine storm during endotoxemia and, in contrast, consistently decreased IL‐33 levels." (PMID 35593197, 2022). "In addition, rIL‐33 pretreatment significantly protected Panx1−/‐ → WT mice against LPS‐induced endotoxemia." (PMID 35593197, 2022). "Furthermore, an orthoptic mouse LT model was established to study the liver‐specific role of the PANX1–IL‐33 axis in LPS‐induced endotoxemia." (PMID 35593197, 2022). "Consequently, we focused on the liver‐specific effects of PANX1 on hepatic resistance to endotoxemia." (PMID 35593197, 2022). "According to previous studies, the exact role of PANX1 in endotoxemia remains controversial." (PMID 35593197, 2022). "Similarly, liver-specific knockout of Panx1 also worsened the outcome of lethal endotoxemia, suggesting that Panx1 may still be needed for mounting potentially protective innate immune responses against lethal bacterial infections." (PMID 39763679, 2024). "However, the exact role of PANX1‐ATP signalling in LPS‐induced endotoxemia remains controversial." (PMID 35593197, 2022).
endotoxemia (continued). "Here, we studied a novel mechanism by which the hepatic PANX1–IL‐33 axis is regulated by the ATP‐P2X7 pathway, targeting adaptive immunity in LPS‐induced endotoxemia; these findings supplement our previous study and others." (PMID 35593197, 2022).
hearing loss (3 papers, 2015 to 2018). "Recent studies demonstrated that Pannexin-1 (Panx1) deficiency in mice and mutation in humans are also associated with hearing loss." (PMID 29710868, 2018). "In this study, we found that the Gen-Panx1 KO mouse had hearing loss." (PMID 29710868, 2018). "These new data further confirm that Panx1 deficiency can induce hearing loss." (PMID 29710868, 2018). "These new findings strongly suggest that Panx1 mutations may also be able to induce hearing loss in humans, which requires further study in future." (PMID 27229462, 2016). "Panx1 deficiency can reduce ATP release and EP generation causing hearing loss." (PMID 26035172, 2015). "In this study, we found that Panx1 deficiency can cause hearing loss." (PMID 26035172, 2015). "However, it was for a long-time undetermined whether Panx deficiency can induce hearing loss, until recent studies showing that Panx1-deficient mice and mutation in humans are associated with deafness." (PMID 29710868, 2018).
Insulin resistance (3 papers, 2021 to 2025). Increased resistance towards insulin, that is, diminished effectiveness of insulin in reducing blood glucose levels. "Increased glucose production and insulin resistance in PANX1-deficient mice were not affected by AAV-FAM3A injection." (PMID 38937853, 2024). "Adipocyte-specific PANX1 knockout exacerbated HFD-induced global insulin resistance." (PMID 38937853, 2024). "Since insulin activates PANX1 channels causing the release of ATP, which in turn results in a signaling cascade indirectly allowing the transport of glucose into adipocytes, PANX1 might play a role in sustaining the inflammation observed during insulin resistance." (PMID 34975840, 2021).
intracerebral hemorrhage (3 papers, 2020 to 2024). A cerebrovascular disorder characterized by bleeding into one or both cerebral hemispheres including the basal ganglia and the cerebral cortex. "It was found that inhibition of pannexin-1 significantly alleviated neuronal apoptosis and degeneration in rats with intracerebral hemorrhage." (PMID 38803679, 2024). "In line with the results in human traumatic brain injury, serum pannexin-1 concentrations increases after intracerebral hemorrhage, hinting that serum pannexin-1 may be at least partially originated from central nervous system." (PMID 38803679, 2024). "Pharmacological inhibition of Panx1 alleviated tissue damage in rats with intracerebral hemorrhage." (PMID 32819386, 2020).
liver diseases (3 papers, 2023 to 2024). "As demonstrated for the case of liver disease, the Panx1-targeting nanobodies hold great promise as anti-inflammatory agents, yet this should be further tested for extrahepatic inflammatory disorders." (PMID 37821897, 2023). "Consequently, Panx1 channels are regarded as key determinants in the induction and propagation of inflammation and cell death processes, being hallmarks of a plethora of liver diseases." (PMID 37492223, 2023).
myocardial infarction (3 papers, 2013 to 2023). Gross necrosis of the myocardium, as a result of interruption of the blood supply to the area, as in coronary thrombosis. "Furthermore, Panx1 channels were identified as mediators of neuroinflammation and act as drives of inflammation in acute myocardial infarction." (PMID 36950521, 2023). "An important role for Panx1 in inflammation has been observed especially for endothelial cells, because Panx1 at the plasma membrane of these cells mediates vascular inflammation during lung ischemia-reperfusion injury and regulates cardiac responses to acute myocardial infarction." (PMID 36950521, 2023).
neuropathy (3 papers, 2017 to 2022). A disorder affecting the nervous system that manifests with pain, tingling, numbness, and/or muscle weakness. "Here, we used global Panx1 knockout mice (Panx1−/−) and two sciatic nerve injury models of trauma-induced neuropathy to provide genetic evidence for a major role of Panx1 in neuropathic pain." (PMID 28195232, 2017). "The high comorbidity between some neuropathies can be partially understood by the fact that these diseases share a common etiology involving inflammatory pathways and Panx1 channels or Cx43 HCs." (PMID 29066951, 2017). "In this study, we present evidence that, in neuropathy, NMDAR- and P2X7R-mediated pronociceptive effects are dependent on concomitant Panx1 channel activity." (PMID 35743148, 2022).
Obesity (3 papers, 2018 to 2022). Accumulation of substantial excess body fat. "Panx1 regulates the proliferation and differentiation of murine ASCs, and the germline deletion of Panx1 results in increased fat mass in vivo, underlining a role for Panx1 in fat accumulation and obesity." (PMID 30385873, 2018). "Another study found that palmitate, a saturated fatty acid, can upregulate pannexin-1 channels in macrophages, and also found that macrophages attract neutrophils into metabolic tissues during obesity by releasing nucleotides." (PMID 34421909, 2021). "Another study found that palmitate, a free fatty acid, can promote macrophages to release nucleotides, which are neutrophil chemotactic factors, through the pannexin-1 channel, a process that may facilitate the recruitment of neutrophils into metabolic tissues during obesity." (PMID 34421909, 2021). "Taken together, we have identified Panx1 as a novel regulator of ASC proliferation and adipogenic differentiation, and consequently, a key component of the regulation of fat accumulation, representing a potential new target for obesity intervention." (PMID 30385873, 2018).
retinal ischemia (3 papers, 2012 to 2023). A ischemic disease that involves the retina. "In the model of retinal ischemia-reperfusion, Panx1-mediated neurotoxicity correlated with robust activation of endogenous, neuronal inflammasome and the release of IL-1β in the ganglion cell layer, the site of major damage." (PMID 24575045, 2014). "In this study, we investigated the role of the Panx1 channel in the pathophysiology of global retinal ischemia followed by reperfusion." (PMID 22384122, 2012). "To study the role of Panx1 channels in retinal ischemia we generated homozygous Panx1fl/fl (“floxed”) mutant mice, harboring three LoxP consensus sites inserted into a single-copy Panx1 gene (Panx1/LoxP line)." (PMID 22384122, 2012). "We demonstrated that Panx1 in RGCs contributes to pathophysiology of acute retinal ischemia." (PMID 22384122, 2012). "To test this hypothesis, we induced experimental retinal ischemia followed by reperfusion in live animals with the Panx1 channel genetically ablated either in the entire mouse (Panx1 KO), or only in neurons using the conditional knockout (Panx1 CKO) technology." (PMID 22384122, 2012).
type 2 diabetes mellitus (3 papers, 2022 to 2026). A type of diabetes mellitus that is characterized by insulin resistance or desensitization and increased blood glucose levels. "In addition, our data suggest that glomerular Panx1 expression is a potential indicator of worsening renal function in patients with type 2 diabetes." (PMID 35625681, 2022).
adenocarcinoma of gallbladder (2 papers, 2016 to 2023). "The immunohistochemical study of Panx-1 with Ki-67 in human gallbladder and gallbladder adenocarcinomas showed that Panx1 expression negatively correlated with proliferation in gallbladder carcinomas." (PMID 36833374, 2023).
Arrhythmia (2 papers, 2020 to 2022). Any cardiac rhythm other than the normal sinus rhythm. "Dysregulated Cx43 expression and topology combined with HCs and Panx1 channel activation impairs both GJCs and ion channel function and promotes life-threatening arrhythmias." (PMID 33383853, 2020).
Arthritis (2 papers, 2013 to 2021). Inflammation of a joint. "Advantages of Panx1 as a drug target are that it is accessible to drugs and Panx1 inhibitors are already available and FDA approved, such as the anti-malaria drug mefloquine and the gouty arthritis drug probenecid." (PMID 23675350, 2013).
autoimmune (2 papers, 2021 to 2025). "This dual behavior, observed in models of autoimmunity, infection, neuroinflammation, and cancer, underscores the complexity of its biological role and the importance of context when considering Panx1 as a therapeutic target." (PMID 40978734, 2025).